OR2D3 (olfactory receptor family 2 subfamily D member 3)
Description:
Odorant receptor.
Synonyms: OR11-89
Tractability: Antibody: UniProt places it where antibodies can reach, with medium confidence; UniProt predicts a signal peptide or a membrane-spanning region; its Gene Ontology location is reachable by antibodies, with medium confidence.
Gene: Protein-coding gene on chromosome 11 (6,921,002 to 6,921,994, forward strand). Ensembl gene ENSG00000178358.
Subcellular location: Cell membrane
Pathways (Reactome):
Sensory Perception: Expression and translocation of olfactory receptors
Gene Ontology:
Molecular function: olfactory receptor activity; G protein-coupled receptor activity
Biological process: detection of chemical stimulus involved in sensory perception of smell; G protein-coupled receptor signaling pathway
Cellular component: plasma membrane; membrane
Genetic constraint (gnomAD): Loss-of-function variants: 7 observed, 6.84 expected, observed/expected ratio (o/e) 1.02, 90% interval 0.58 to 1.77. That is too few expected variants to judge how well the gene tolerates losing a copy. Missense variants: 409 observed, 406.02 expected, observed/expected ratio (o/e) 1.01, 90% interval 0.93 to 1.09. Synonymous variants: 154 observed, 152.42 expected, observed/expected ratio (o/e) 1.01, 90% interval 0.88 to 1.15.
Homologues: Orthologues: chimpanzee OR2D3 (98% identical), macaque OR2D3 (92% identical), dog OR2D3 (84% identical), dog OR2D3F (82% identical), rat Or2d36 (76% identical), mouse Or2d36 (76% identical), rat Or2d36b (75% identical). Paralogues in human: OR2D2 (59% identical), OR2F1 (50% identical), OR2F2 (50% identical), OR2B3 (47% identical), OR2G6 (47% identical), OR2G3 (46% identical), OR13D1 (46% identical), OR2B2 (46% identical), OR2S2 (46% identical), OR2J2 (45% identical), OR2Y1 (45% identical), OR5V1 (45% identical), and 80 more.